REST (RE1 silencing transcription factor)
Diseases named in the same sentence as REST in open-access papers (continued):
Sharing a sentence is not in itself a finding about the gene and the disease.
glioma (continued). "In this study, we found an upregulation of REST expression in 9 cancer types and the prognostic value of REST in 6 cancer types, suggesting an oncogenic function of REST in tumors, especially in gliomas." (PMID 36810892, 2023). "Taken together, our findings suggest that the protein expression level of REST correlate with clinical prognosis and tumor immune infiltration in patients with glioma." (PMID 36810892, 2023). "The functions of REST in various tumors have been studied, but its role and correlation with immune cell infiltration remains uncertain in gliomas." (PMID 36810892, 2023). "Then we investigated the relationship between REST expression and immune infiltration, biomarkers of immune cells, and immune checkpoints in glioma." (PMID 36810892, 2023). "Considering the potential oncogenic role of REST in glioma, the relationship of REST with PD1, PD-L1, or CTLA-4 was assessed." (PMID 36810892, 2023). "Taken together, miR-9-5p and miR-105-5p/REST axis were identified as potential regulatory pathways in glioma, representing a novel potential treatment strategy for glioma." (PMID 36810892, 2023). "In this study, we presented evidence of histone deacetylase 1 (HDAC1) as a potential REST-binding protein and the REST expression-correlated gene in glioma through a series of pathway enrichment analyses." (PMID 36810892, 2023). "To further explore the role of REST in tumor immune, we determined the expression correlation of REST with biomarkers of immune cells in glioma." (PMID 36810892, 2023). "As it is difficult to get hold of glioma cells, we performed in vitro experiments with REST in U251 and T98G cell lines to verify the effectiveness of the predicted upstream miRNAs of REST and their regulatory relationship." (PMID 36810892, 2023). "In conclusion, we conducted comprehensive pan-cancer analyses of REST, revealing that REST was differentially expressed between tumor and normal tissues and acted as an independent prognostic indicator of various tumors, especially glioma." (PMID 36810892, 2023). "To explore the relationship between REST expression and prognosis of glioma patients, we analyzed the correlation of REST expression with OS, PFI and DSS." (PMID 34859007, 2021). "We downloaded RNA-seq, miRNA-seq and correlated clinical data of 670 glioma patients from The Cancer Genome Atlas and analyzed the correlation between REST expression, clinical characteristics and prognosis." (PMID 34859007, 2021). "Results showed that REST expression was significantly higher in glioma patients than normal samples." (PMID 34859007, 2021). "The representative results showed that REST was not expressed in normal brain tissue, whereas high expression of REST was observed in glioma tissue." (PMID 34859007, 2021). "In terms of CNS tumors, REST has been confirmed to play key roles in glioma, although further bioinformatic analysis of distinct roles of REST in glioma remained elusive." (PMID 34859007, 2021). "To further explore the biological function of REST in glioma, we grouped the expression profiles according to the level of REST expression." (PMID 34859007, 2021). "High REST expression was significantly associated with worse OS, worse PFI, and worse DSS in glioma patients." (PMID 34859007, 2021). "The objective of this study was to systematically clarify the clinical relevance, gene functions, and ceRNA regulatory network of REST in glioma." (PMID 34859007, 2021). "To analyze the difference in REST expression between gliomas and normal tissues, we used the TCGA database combined with GTEX data to analyze the gene expression level of REST in pan-cancer and adjacent tissues." (PMID 34859007, 2021). "EZH2, NFE2L2, REST, SMAD4 and SUZ12 were all implicated as common transcriptional regulators of DEGs in glioma, sarcoma, breast and stomach cancers, suggesting that altered AMPK signaling converged on similar groups of transcriptional targets." (PMID 32807122, 2020).
glioma (continued). "Other authors have confirmed the existence of three different subgroups among IDHmut gliomas, underlying the key role of other epigenetic modulators apart from mutant IDH1/2, like REST (RE1 Silencing Transcription Factor), in some of these subgroups." (PMID 32570988, 2020). "Apart from that, REST has also been identified as a specific marker for glioma subtyping due to its epigenetic alteration pattern." (PMID 31803734, 2019). "Recently, a role for REST was suggested in glioma with REST up-regulation able to drive cell proliferation and suppress differentiation." (PMID 23216891, 2012). "Our results suggest that, in glial cells, both REST and CoREST modulate genes in key pathways responsible for the formation of glial tumors, such as glioblastoma multiforme (GBM)." (PMID 19888342, 2009). "Another study revealed that pioglitazone, a peroxisome proliferator-activated receptor-γ (PPARγ) agonist and an antihyperglycemic drug against type 2 diabetes as well as an antineoplastic drug, inhibit proliferation and induce apoptosis of glioma cells by down-regulating REST mRNA." (PMID 40006989, 2025). "An enrichment analysis of REST emphasized the significance of chromatin organization and histone modification, suggesting a possible involvement of the Hedgehog-Gli pathway in REST’s role in glioma pathogenesis." (PMID 38534769, 2024). "REST knockdown differently impacted invasion of the parental or IDH1 mutant glioma cells." (PMID 38711090, 2024). "To verify whether differentially methylated motif sites affect expression of REST targets, we calculated correlation between mean methylation and gene expression using the glioma Atlas and TCGA datasets." (PMID 38711090, 2024). "We further examined REST expression in 70 glioma tissue specimens from our glioma bank." (PMID 39039049, 2024). "Thus, we studied DNA methylation patterns within individual motifs for the REST or KAISO TFs across gliomas using the DiffMeth tool and methylomes of IDH-MUT, G2/G3 IDH-WT and G4 IDH-WT gliomas from the glioma Atlas." (PMID 38711090, 2024). "REST knockdown in U87 glioma cells affected many biological pathways." (PMID 38711090, 2024). "Additionally, most of the primary repressed REST targets were consistently downregulated in gliomas compared to normal brain samples, with expression decreasing from G2 and G3 to G4." (PMID 38711090, 2024). "In addition to its role in cell proliferation, REST has been previously shown to be a key driver of glioma cell migration." (PMID 39602392, 2024). "Intermediate expression of REST in G2/G3 gliomas may be enough to maintain a higher expression of the genes contributing to the NPC-like state." (PMID 38711090, 2024). "In keeping with this hypothesis, a recent study showed that REST silencing down-regulates several pathways involved in glioma cell mitosis and cell proliferation." (PMID 39602392, 2024). "It is therefore conceivable that REST promotes glioma progression by down-regulating HAR1A." (PMID 39602392, 2024). "Our results point to REST as a valid target in anti-glioma therapy." (PMID 38711090, 2024). "Overall, our results show that REST exerts pleiotropic pro-oncogenic functions in gliomas, as shown by its pro-survival and anti-apoptotic effects, and by its higher expression in invasive glioma cells." (PMID 39602392, 2024). "Following the linear regression analysis of HAR1A, HAR1B, and REST, we determined whether aberrant expression of these lncRNAs and REST impacted glioma patient prognosis, using a Kaplan Meier analysis." (PMID 39602392, 2024). "In gliomas REST acts as an oncogene and is a potential therapeutic target." (PMID 39602392, 2024). "However, a large subset of DEGs between IDH-WT and IDH-MUT U87 glioma cells were differently affected by REST knockdown." (PMID 38711090, 2024). "Importantly, the effective regulation of miR-9-5p and miR-105-5p on REST expression and the proliferation and migration of glioma cells were experimentally validated." (PMID 36810892, 2023).
glioma (continued). "Thus, the expression correlation analysis showed that 7 of 41 miRNAs were significantly negatively correlated with the REST in glioma (P < 0.05)." (PMID 36810892, 2023). "The REST seemed to be identified as a potential therapeutic target for glioma treatment." (PMID 36810892, 2023). "All these findings suggest that miR-105-5p and miR-9-5p might be the potential regulatory miRNAs of REST in glioma." (PMID 36810892, 2023). "REST expression was significantly associated with all analyzed immune cells, including B cells, CD8+ T cells, CD4+ immune cells, macrophages, neutrophils, and dendritic cells in glioma (P < 0.001)." (PMID 36810892, 2023). "Taken together, these results suggest that REST may mediate the carcinogenesis of glioma by the mechanism of tumor immune escape, and targeting REST might increase the efficacy of immunotherapy in glioma." (PMID 36810892, 2023). "Overall, these findings indicated that REST may alter tumor immune microenvironment, and immune cell infiltration might participate in REST-mediated oncogenic roles in glioma." (PMID 36810892, 2023). "REST is highly expressed in glioma, and its interference inhibits tumors." (PMID 37892159, 2023). "Our results strongly suggested that REST may be used as a potential prognostic and immunological biomarker in glioma." (PMID 36810892, 2023). "Moreover, IHC staining was conducted to evaluate the expression of REST and CD4 in normal and glioma tissues with different REST expression." (PMID 36810892, 2023). "Therefore, the knowledge of REST in tumors, especially in glioma, remains inadequate and needs to be further investigated." (PMID 36810892, 2023). "Our study suggests REST to be an oncogenic gene and the biomarker of poor prognosis in glioma." (PMID 36810892, 2023). "Chromatin organization and histone modification were the most significant enriched terms, and Hedgehog-Gli pathway might be involved in the effect of REST on the pathogenesis of glioma (P < 0.01)." (PMID 36810892, 2023). "Furthermore, HDAC1 was the potential REST-binding protein and the REST expression-correlated gene in glioma." (PMID 36810892, 2023). "The molecular mechanism of REST effect on the pathogenesis of glioma was also analyzed." (PMID 36810892, 2023). "Thus, the effect of REST on Hedgehog-Gli pathway during the pathogenesis of glioma requires further investigation." (PMID 36810892, 2023). "REST mediated the inhibition of proliferation of glioma by pioglitazone." (PMID 37892159, 2023). "Our research further clarified that Hedgehog-Glioma-associated oncogene homolog (Hedgehog-Gli) pathway might be involved in the effect of REST on the pathogenesis of glioma." (PMID 36810892, 2023). "In addition, we explored the protein expression of REST in glioma and normal samples and examined the immunohistochemical results of REST protein using the HPA." (PMID 34859007, 2021). "REST has been considered an important therapeutic target for the treatment of glioma." (PMID 34859007, 2021). "Furthermore, we observed that REST expression level in glioma (LGG + GBM) was significantly higher than that in normal samples." (PMID 34859007, 2021). "Our findings may provide new insights into the clinical prognostic value and regulatory mechanisms of REST in glioma." (PMID 34859007, 2021). "Moreover, we identified a set of TFs which putatively regulate gene expression in multiple TADs, including known glioma related TFs such as REST, E2F1 and NFKB1." (PMID 34341417, 2021). "Thus, REST could be utilized as a potential therapeutic target for the treatment of glioma patients." (PMID 40006989, 2025). "Next, we investigated whether REST expression had a prognostic value in glioma patients' survival." (PMID 38711090, 2024). "We conclude that REST could be an important therapeutic target in gliomas." (PMID 38711090, 2024).
glioma (continued). "Also, given the known role of REST in glial migration, and its up-regulation in invasive glioma cells, it would have been interesting to test whether silencing this gene affected the migratory properties of invasive glioma cells." (PMID 39602392, 2024). "Finally, repression of the canonical REST gene targets may play a more significant role in IDH-MUT grade 2/3 gliomas than in G4 gliomas by maintaining NPC-like cellular state properties." (PMID 38711090, 2024). "High REST expression might affect the tumor microenvironment of glioma." (PMID 36810892, 2023). "Enrichment analysis of REST found chromatin organization and histone modification were the most significant enriched terms, and Hedgehog-Gli pathway might be involved in the effect of REST on the pathogenesis of glioma." (PMID 36810892, 2023). "In addition, Hedgehog-Gli pathway might be involved in the effect of REST on the pathogenesis of glioma." (PMID 36810892, 2023). "Furthermore, our enrichment and pathway analyses indicated that REST potentially impacts the etiology or pathogenesis of glioma might by functioning in chromatin organization, histone H4 deacetylation, and Sin3 complex." (PMID 36810892, 2023). "REST may be a prognostic biomarker and potential target of glioma." (PMID 34859007, 2021). "Thus, REST may be a prognostic biomarker and therapeutic target in glioma, and its regulatory network validated in this study may provide insights into glioma's molecular regulatory mechanisms." (PMID 34859007, 2021). "Therefore, we finally obtained two REST-related ceRNA regulatory networks in glioma cell lines." (PMID 34859007, 2021). "Thus, REST may be a prognostic biomarker and target in glioma, and the network validated in this study may provide insights into glioma's molecular regulatory mechanisms." (PMID 34859007, 2021). "Alterations identified by Titan-CNA in the 4q12 MCR covered recognized oncogenes and genes with known biological significance in glioma and glioblastoma, including PDGFRA, REST, and CLOCK9,23,24." (PMID 40319462, 2025). "After modulating REST expression, we found that erianin indeed inhibiting TMZ-resistant gliomas and induces ferroptosis through REST." (PMID 39039049, 2024). "We studied the effects of REST knockdown, genome wide occurrence of REST binding sites, and DNA methylation of REST motifs in IDH wild type and IDH mutant gliomas." (PMID 38711090, 2024). "While in all gliomas (LGG and GBM) REST expression was inversely correlated with patients survival as previously reported, we found that its high expression is an unfavorable prognostic factor in LGG with the IDH mutation, but a favorable factor in GBM." (PMID 38711090, 2024). "In summary, we identified REST targets, gene regulatory networks and putative REST cooperativity with other TFs that differentially control gene expression in IDH-WT and IDH-MUT gliomas." (PMID 38711090, 2024). "Consistent with our results, high expression of HDAC1, CASP3, REST, GNAI3, FZD1, EPHB4 was found to correlate with poor prognosis of glioma, and inhibitors of HDAC1 inhibited the EMT process in glioma cells thereby affecting cell migration and invasion." (PMID 38629068, 2024). "Exploration of TCGA datasets showed increased REST expression in malignant gliomas and decreased REST expression in IDH-mutant when compared to IDH-WT gliomas." (PMID 38711090, 2024). "In our study, REST knockdown increased expression of ECM related genes and invasion of IDH-MUT glioma cells, which coincided with changes in promoter and gene body methylation in more than half of the cases." (PMID 38711090, 2024). "We analyzed REST expression in The Cancer Genome Atlas (TCGA) transcriptomic data encompassing normal brain (NB) tissues, LGG (Lower Grade Gliomas, WHO grades 2 and 3) and GBM (glioblastoma, WHO grade 4) samples." (PMID 38711090, 2024). "Here we show that the CPLX1 gene is suppressed by REST and that higher CPLX1 expression predicts better prognosis in gliomas." (PMID 39602392, 2024).
glioma (continued). "We performed KAISO silencing in U87 cells to determine a potential overlap between REST and KAISO gene targets in glioma cells." (PMID 38711090, 2024). "In the lower grade glioma dataset, we found that a poorer prognosis of patients correlated with low expression of HAR1A and HAR1B, and with high expression of REST." (PMID 39602392, 2024). "The differences in the number of ChIP-seq peaks and in genomic distribution of DNA binding sites between IDH-WT and IDH-MUT suggest a stronger transcriptional regulation by REST (including both repression and activation) in IDH-WT glioma cells." (PMID 38711090, 2024). "REST expression was positively correlated with infiltration of immune cells and the expression of immune checkpoints such as PD1/PD-L1 and CTLA-4 in glioma." (PMID 36810892, 2023). "We found that the expression level of REST protein was significantly positively correlated with PD1, PD-L1, and CTLA-4 in glioma, which was adjusted by purity (P < 0.001)." (PMID 36810892, 2023). "Therefore, it is possible that REST may play an oncogenic role in glioma." (PMID 36810892, 2023). "Differently, another study by gene copy number analyses showed that most gliomas expressed low amplification of REST17, indicating that the oncogenic role of REST still remains controversial." (PMID 36810892, 2023). "We found the set of transcription factors, including REST, E2F1 and NFKB1, that are most likely to regulate gene expression in multiple TADs, containing specific glioma-related genes." (PMID 34341417, 2021). "We detected TF binding sites for E2F1, HMX1, PAX5, REST and ZBTB6 in the promoters of DEGs present within the top six ‘glioma TADs’." (PMID 34341417, 2021). "While it functions as a tumor suppressor in prostate, colon, breast and lung epithelial cells, where it protects from neuroendocrine transformation, REST/NRSF shows tumor-promoting functions in medulloblastoma and glioma, ovarian and pancreatic cancers." (PMID 32244895, 2020). "REST, targeted by probes named as cg26694713 and cg04360458, is also predicted to participate in IDH-dependent glioma subtyping." (PMID 31803734, 2019). "The most important methylation feature (cg15072976) overlaps with the RE1 Silencing Transcription Factor (REST) binding site, and was confirmed to intersect with the REST binding motif in human U87 glioma cells." (PMID 29535343, 2018). "As expected, REST suppresses the expression of HAR1A in both pediatric and adult glioma cells." (PMID 39602392, 2024). "For example, REST downregulates synapsin-1 (SYN1), contributing to glioma pathogenesis." (PMID 39602392, 2024). "Viability of both IDH-WT and IDH-MUT U87 glioma cells was not significantly affected by REST knockdown post-transfection as measured with the PrestoBlue assay." (PMID 38711090, 2024). "Increased REST expression in G4 IDH-WT gliomas and decreased in IDH-MUT gliomas may result in REST binding to the sites that are otherwise occupied by other TFs with a different mode of action." (PMID 38711090, 2024). "We found that REST expression is a strong negative prognostic factor for patient’s survival in all gliomas (LGG and G4 samples)." (PMID 38711090, 2024). "Our results show that REST and HAR1A are negatively correlated in gliomas." (PMID 39602392, 2024). "Some of the genes defined as REST-activated targets (i.e. NTF3 and GLI3) containing KAISO motifs within the REST ChIP-seq peaks had a methylation pattern similar to the repressed REST targets across glioma tumor types." (PMID 38711090, 2024). "The identified REST targets, gene regulatory networks and putative REST cooperativity with other TFs, including KAISO, point to distinctiveness of the REST regulome in IDH-WT and IDH-MUT gliomas." (PMID 38711090, 2024). "DNA methylation within REST motifs of REST ChIP-seq peaks containing both KAISO and REST motifs showed significantly higher DNA methylation in peaks assigned to repressed REST targets only in G4 IDH-WT gliomas." (PMID 38711090, 2024).